LPP-AS2 (LPP antisense RNA 2)
Synonyms: MYCLo-5; MYCLo-6
Gene: Long non-coding RNA gene on chromosome 3 (188,151,206 to 188,154,087, reverse strand). Ensembl gene ENSG00000270959.
Diseases named in the same sentence as LPP-AS2 in open-access papers:
LPP-AS2 is named in the same sentence as 4 diseases in open-access papers, as found by Europe PMC text mining. Sharing a sentence is not in itself a finding about the gene and the disease. The quoted sentences say what the papers report.
colorectal cancer (1 paper, 2020). A primary or metastatic malignant neoplasm that affects the colon or rectum. "It has been reported that c-MYC inhibited the expression of LPP-AS2 in colorectal cancer." (PMID 32962742, 2020).
glioblastoma (1 paper, 2020). The most malignant astrocytic tumor (WHO grade IV). "This upregulated expression of LPP-AS2 was observed to be related to poor prognosis and adverse clinical survival among patients with glioblastoma." (PMID 32962742, 2020). "Nevertheless, it remains unclear whether c-MYC is able to transcriptionally regulate expression of LPP-AS2 in glioblastoma." (PMID 32962742, 2020). "However, the function and molecular mechanism of LPP-AS2 in tumors, including glioblastoma, have not been elucidated to date." (PMID 32962742, 2020).
glioma (1 paper, 2020). A benign or malignant brain and spinal cord tumor that arises from glial cells (astrocytes, oligodendrocytes, ependymal cells). "Besides, expression of LPP-AS2 was significantly elevated in seven glioma cell lines (U251, SHG44, T98G, U373, U87, GOS-3, and TJ905) compared to the normal cell line HEB and was higher in the U251 and SHG44 cell lines." (PMID 32962742, 2020). "Notably, we found the expression of LPP-AS2 was markedly increased in 106 glioma tissues (12 Grade I, 15 Grade II, 30 Grade III and 49 Grade IV) compared with 23 normal brain tissues by RT-qPCR." (PMID 32962742, 2020). "More importantly, we found that c-MYC could regulate expression of LPP-AS2, suggesting that LPP-AS2 is transcriptionally regulated by c-MYC, and functions as an oncogene in glioma via an miR-7-5p/EGFR/PI3K/AKT/c-MYC feedback loop." (PMID 32962742, 2020). "Expression of LPP-AS2, epidermal growth factor receptor (EGFR) and miR-7-5p in glioma tissues and cell lines was detected by real-time quantitative PCR (RT-qPCR), and the functions of lncRNA LPP-AS2 in glioma were assessed by in vivo and in vitro assays." (PMID 32962742, 2020).
LPP-AS2 also shares sentences with these, for which no sentence is quoted: tumor (1 paper).